IDI1 (isopentenyl-diphosphate delta isomerase 1)
Description:
Catalyzes the 1,3-allylic rearrangement of the homoallylic substrate isopentenyl (IPP) to its highly electrophilic allylic isomer, dimethylallyl diphosphate (DMAPP).
Synonyms: IPPI1; IPP1
Tractability: Small molecule: a structure with a bound ligand is known; it has a high-quality binding pocket. PROTAC: ubiquitination databases record sites on it; its protein half-life has been measured.
Gene: Protein-coding gene on chromosome 10 (1,039,152 to 1,049,119, reverse strand). Ensembl gene ENSG00000067064.
Subcellular location: Peroxisome
Pathways (Reactome):
Metabolism: Activation of gene expression by SREBF (SREBP); Lanosterol biosynthesis
Gene Ontology:
Molecular function: isopentenyl-diphosphate delta-isomerase activity; intramolecular oxidoreductase activity
Biological process: cholesterol biosynthetic process; dimethylallyl diphosphate biosynthetic process; farnesyl diphosphate biosynthetic process, mevalonate pathway; geranylgeranyl diphosphate biosynthetic process; isoprenoid biosynthetic process; response to stilbenoid; zymosterol biosynthetic process
Cellular component: peroxisome; cytosol
Genetic constraint (gnomAD): Loss-of-function variants: 9 observed, 17.22 expected, observed/expected ratio (o/e) 0.52, 90% interval 0.31 to 0.91. The upper end of that interval is the gene's LOEUF score, 0.91, which puts it in group 3 of 6, group 1 being the genes least tolerant of losing a copy. Missense variants: 251 observed, 240.95 expected, observed/expected ratio (o/e) 1.04, 90% interval 0.94 to 1.16. Synonymous variants: 99 observed, 86.89 expected, observed/expected ratio (o/e) 1.14, 90% interval 0.97 to 1.35.
Homologues: Orthologues: chimpanzee IDI1 (99% identical), rat Idi1 (78% identical), macaque IDI1 (77% identical), dog IDI1 (71% identical), guinea pig IDI1 (70% identical), pig IDI1 (70% identical), mouse Idi1 (69% identical), zebrafish idi1 (63% identical), tropical clawed frog idi1 (62% identical), Drosophila melanogaster Idi (40% identical), Caenorhabditis elegans idi-1 (31% identical). Paralogues in human: IDI2 (52% identical).
Diseases named in the same sentence as IDI1 in open-access papers:
IDI1 is named in the same sentence as 34 diseases in open-access papers, as found by Europe PMC text mining. Sharing a sentence is not in itself a finding about the gene and the disease. The quoted sentences say what the papers report.
breast carcinoma (2 papers, 2021 to 2022). "In this sense, it has been demonstrated through microarrays and the RT-qPCR gene expression analysis, that cell treatments with HMGCR inhibitors, differentially induces the expression of HMGCR, HMGCS1 and IDI1 genes in breast cancer cell lines." (PMID 35359411, 2022). "We consulted the Human Protein Atlas Interactive Analysis to validate the expression of the core driver genes, including IDI1, BNIP3, IFRD1, COQ10B, and ZBTB10, at the protein and RNA levels in breast cancer." (PMID 34226298, 2021).
lung carcinoma (2 papers, 2011 to 2015). "Further studies showed that treatment of lung cancer cells with miR-197 led to decreases in expression of HMGCoA-R, HMGCoA-S1, and isopentenyl-diphosphate delta isomerase 1 (IDI1)." (PMID 26226008, 2015).
Obesity (2 papers, 2018 to 2022). Accumulation of substantial excess body fat. "Furthermore, PLAGL1 may be implicated in lipid metabolism and obesity through its effect on IDI1, PNPLA1, JAK3, and RAB37 expression." (PMID 30082726, 2018).
amyotrophic lateral sclerosis (1 paper, 2021). Amyotrophic lateral sclerosis (ALS) is a neurodegenerative disease characterized by progressive muscular paralysis reflecting degeneration of motor neurons in the primary motor cortex, corticospinal tracts, brainstem and spinal cord. "IPP is increased when the genes for the enzymes that process it like isopentenyl diphosphate isomerase 1 and 2 (IDI1 and IDI2) are disrupted in a copy number variant in amyotrophic lateral sclerosis, or when the protein is aggregated in Lewy bodies in the brain." (PMID 33735311, 2021).
anorexia nervosa (1 paper, 2022). A disorder most often seen in adolescent females characterized by a refusal to maintain a minimally normal body weight, an intense fear of gaining weight, a disturbance in body image, and, in postmenarcheal females, the development of amenorrhea. "In addition, IDI1 was associated with multiple mental disorders (obsessive compulsive disorder, anorexia nervosa, bipolar disorder, and general mood disorders), consistent with its TWAS associations with fluid intelligence and schizophrenia." (PMID 35121757, 2022).
bacterial sepsis (1 paper, 2020).
cataract (1 paper, 2022). Partial or complete opacity of the crystalline lens of one or both eyes that decreases visual acuity and eventually results in blindness. "SCR rats that are genetically predisposed to cataracts are reported to have mutations in Lss and Fdft1, which encode lanosterol synthase and farnesyl diphosphate farnesyltransferase, respectively, and which, like Hmgcs1 and Idi1, are involved in the cholesterol synthesis pathway." (PMID 36477544, 2022).
cholestasis (1 paper, 2023). Impairment of the bile flow caused by obstruction within the liver, or outside the liver in the bile duct system. "Based on the analysis of the experimental results, we confirmed that SHCZF can indeed improve cholestasis and subsequent hepatic inflammation and injury by regulating IDI1/SREBP2 pathway." (PMID 36843951, 2023). "IDI1 and SREBP2 are the crucial target genes of SHCZF for the treatment of cholestasis, as clarified by bioinformatics and literature analysis." (PMID 36843951, 2023).
cutaneous sarcoidosis (1 paper, 2024).
gastric cancer (1 paper, 2025). A primary or metastatic malignant neoplasm involving the stomach. "Within this pathway, the roles of farnesyl diphosphate synthase (FDPS), isopentenyl-diphosphate delta isomerase 1 (IDI1), and SQLE in gastric cancer remain largely unexplored." (PMID 39809787, 2025).
hyperlipidemia (1 paper, 2022). "The mechanism of CF to improve hyperlipidemia is very complex, mainly involving biological processes such as cholesterol and fatty acid metabolism and glycolysis, including 41 differential genes such as Sqle, Gck, and Idi1." (PMID 36147301, 2022).
intrahepatic cholestasis (1 paper, 2023). A cholestasis characterized by impairment of the bile flow caused by obstruction located in the liver. "Sequencing and bioinformatics analysis suggested that IDI1 and SREBP2 are hub target genes of SHCZF to ameliorate ANTI-induced intrahepatic cholestasis in rats." (PMID 36843951, 2023).
liver cancer (1 paper, 2024). An epithelial or non-epithelial malignant neoplasm that arises from the liver. "After analyzing six tumor-specific signatures (IDI1, GMPPA, NME1, PSMB3, SPTLC1 and EBP), the gene effect and gene dependency were measured in different non-cancerous cell lines and liver cancer lines of human HCC." (PMID 38927057, 2024).
liver fibrosis (1 paper, 2025). "Further research revealed that exercise training improved liver fibrosis in NASH mice by downregulating lysine methyltransferase 2D (KMT2D)-mediated IDI1 histone methylation, which inhibits apoptosis." (PMID 40182630, 2025).
Neonatal sepsis (1 paper, 2020). Systemic inflammatory response to infection in newborn babies.
ovarian carcinoma (1 paper, 2011). A malignant neoplasm originating from the surface ovarian epithelium. "In HIO-80 cells, there was significant upregulation of genes encoding for proteins associated with ovarian cancer metastasis [SERPINB2/PAI2], metabolic activities [IDI1, PMM2] and gene expression/transcription [PCGF6, ZNF267]." (PMID 22022533, 2011). "The upregulated genes encode for proteins associated with ovarian cancer metastasis [SERPINB2/PAI2], metabolic activities [IDI1, PMM2] and gene expression/transcription [PCGF6, ZNF267]." (PMID 22022533, 2011).
phospholipidosis (1 paper, 2023). "In particular, the upregulation of the genes MSMO1, IDI1, LSS, and HMGCR suggested enhanced synthesis of cholesterol, and the upregulation of FASN suggested an increased synthesis of fatty acids that may in turn induce phospholipidosis." (PMID 37745076, 2023).
sarcopenia (1 paper, 2025). Progressive decline in muscle mass due to aging which results in decreased functional capacity of muscles. "KAT2A, CTNNBIP1, GABARAPL1, SEC31A, the expression of IDI1 was highly significantly elevated (p-value < 0.01) in both the Sarcopenia and Control groups in the Sarcopenia dataset GSE8479." (PMID 41325398, 2025). "In general, the validity of the diagnostic models was evident with the values of the predictive models of IPF; CTH, and IDI1 as well as the models of sarcopenia; FOFOXO1, CTH, HSD11B, GSTK1, and SPTSSA." (PMID 41325398, 2025). "LASSO regression identified CTH and IDI1 for IPF, and FOXO1, CTH, HSD11B1, GSTK1, and SPTSSA for sarcopenia." (PMID 41325398, 2025).
cancer (8 papers, 2017 to 2024). A tumor composed of atypical neoplastic, often pleomorphic cells that invade other tissues. "To date, the function of PCTP and IDI1 in the progression of cancers is still unclear, and further experimental work is needed." (PMID 36826154, 2023). "The expression of IDI-1 in cancer cell lines remains poorly understood." (PMID 39861074, 2024). "These signature included EGFR, COX2, and the matrix metalloproteinases 1 (MMP1), CXCL1 and IDI1 which were highly expressed in the Triple Negative subtype and HER2-positive cancers." (PMID 36761968, 2023). "Immunohistochemistry and RNA expression analysis indicated that IDI1, BNIP3, IFRD1, and ZBTB10 were significantly differentially expressed in cancer and healthy tissues." (PMID 34226298, 2021). "Analysis of data from the Cancer Cell Line Encyclopedia (CCLE) revealed that the expression levels of HMGCS1, HMGCR, IDI1, FDFT1, and SQLE were significantly higher in SCLC cell lines compared to non-small cell lung cancer (NSCLC) cell lines and other cancer cell lines." (PMID 39669201, 2024). "We also identified six predicted SQLE, CCT3, IDI1, GBA, MTR, and NCSTN cancer drug target genes." (PMID 31216110, 2019).
tumor (4 papers, 2020 to 2025). "In light of the recent studies, alteration in the expression of IDI1 has the potential to influence tumor progression and metastasis, and may well provide a hopeful avenue for therapies." (PMID 41325398, 2025). "Regarding mevalonate biosynthesis, it has been shown that IDI1 promotes tumor growth." (PMID 38927057, 2024). "Interestingly, IDI1 represses CCL5- and CXCL10-expressing cells in the tumor microenvironment, increasing the capacity for immune evasion." (PMID 38927057, 2024).
IDI1 also shares sentences with these, for which no sentence is quoted: infection (2 papers); bipolar disorder (1); endometriosis (1); Granuloma (1); Huntington disease (1); Listeria infection (1); melanoma (1); mental disorder (1); mood disorder (1); neurodegenerative disease (1); obsessive-compulsive disorder (1); sarcoidosis (1); schizophrenia (1); Sepsis (1).